INS (insulin)
Diseases named in the same sentence as INS in open-access papers (continued):
Sharing a sentence is not in itself a finding about the gene and the disease.
Hyperglycemia (continued). "Impaired insulin sensitivity alone or in combination with hyperglycemia represents an important trigger that underlies degenerative processes in cardiovascular tissues, specifically, disturbed ECM assembly leading to calcification diabetic patients." (PMID 31949435, 2019). "High blood glucose (hyperglycemia) and low insulin level in blood are also associated with type-1 diabetes condition." (PMID 31645652, 2019). "Insulin administration, especially in the context of hyperkalemia and uncomplicated hyperglycemia, was the most common cause of iatrogenic hypoglycemia." (PMID 31539342, 2019). "Hyperglycemia associated with pasireotide results from the suppression of insulin secretion and decreased incretin response and is reversible upon treatment discontinuation." (PMID 31440946, 2019). "Simplistically, in T2DM, hyperglycemia is caused by the following two reasons: inadequate insulin secretion and insulin resistance (the body cannot fully respond to insulin)." (PMID 31271575, 2019). "Activity of both conventional and novel PKC isoforms is chronically enhanced by hyperglycemia, lipotoxicity and oxidative stress, which has been associated to the cardiovascular complications in the insulin resistant states." (PMID 30787881, 2019). "In murine models of diabetes, reduced sensitivity to insulin is associated with diminished PI3Kα activity which has been linked to both hyperglycemia and arrhythmias." (PMID 31790629, 2019). "Long-term hyperglycemia causing glucotoxicity has also been linked to RhoA-dependent stress fiber formation and diminished glucose-stimulated insulin secretion." (PMID 31075957, 2019). "Various mechanisms underlying the detrimental influence of hyperglycemia under diabetic and/or insulin-resistant conditions on the myocardial function, structure, and energy metabolism have been intensively investigated." (PMID 31262297, 2019). "It is a metabolic disorder characterized by hyperglycemia caused by insufficient insulin secretion and/or insulin action." (PMID 30823412, 2019). "Accordingly, inadequate sleep duration is associated with poor diet quality, decreased insulin sensitivity, hyperglycemia, and prevalent cardiometabolic risk factors." (PMID 30042730, 2018). "Subsequent work has shown that it is not only hyperglycemia but also insulin-induced hypoglycemia that is strongly associated with adverse outcomes." (PMID 29631990, 2018). "This response was associated with a significant increase in hyperglycemia, hyperinsulinemia, glucosuria, hypertriglyceridemia, and worsening insulin tolerance." (PMID 29789270, 2018). "Reduced liver, fat, and muscle uptake of glucose and resultant hyperglycemia are caused by reduced insulin production or cellular resistance to insulin action or a combination of these factors." (PMID 30116189, 2018). "Homeostasis deficiency eventually results in chronic hyperglycemia, which leads to glucose toxicity to organs and tissues, a decrease in insulin secretion, and an increase in insulin resistance in pancreatic β-cells." (PMID 29772703, 2018). "The recovery of β cell area in insulin IHC images also indicated that melatonin maintains glucose homeostasis and decreases the risk of hyperglycemia in smoking rats." (PMID 29437243, 2018). "HAART associated hyperglycemia is probably multifactor in its etiology, affecting glucose metabolism and insulin sensitivity, and altering the activity of glucocorticoid receptors in several tissues including the kidney." (PMID 30627515, 2018). "These mice develop progressive hyperglycemia because of a conformational change in insulin that causes it to misfold and accumulate in the ER." (PMID 29770126, 2018). "The hyperglycemia was resulted from either deficient levels of insulin (type 1 DM) or from defective insulin action (type 2 DM)." (PMID 30524676, 2018). "Hemoglobin A1c, hyperglycemia, case mix index and corticosteroids were associated (p ≤ 0.03) with insulin therapy." (PMID 29255628, 2018).
Hyperglycemia (continued). "From an endocrinological point of view, obesity is strongly associated with elevated baseline insulin levels, peripheral insulin resistance, and hyperglycemia, or, in the worst case, with type II DM." (PMID 29538298, 2018). "In mouse models of insulin-deficient diabetes, it has been shown that leukocytosis (monocytosis and neutrophilia) is hyperglycemia-dependent." (PMID 30618774, 2018). "The abnormal insulin secretion is due to the functional deficit and loss of pancreatic β-cells, which can primarily cause hyperglycemia and subsequently reduce the sensitivity of insulin." (PMID 30595798, 2018). "Because hypoglycemia can be associated with greater inpatient mortality, the basal-bolus insulin treatment approach can provide the best balance between controlling hyperglycemia while decreasing the risk of hypoglycemia." (PMID 29255628, 2018). "Use of the subcutaneous basal-bolus regimen with once-daily basal insulin and rapid-acting insulin injections before meals has improved hospital hyperglycaemias and has resulted in reduced risk of complications during the hospitalization." (PMID 30208631, 2018). "G/A ratio has been proposed as a marker of postprandial hyperglycemia, glycemic excursion, and decreased insulin secretion capacity, which was also associated with the presence of DKD8,10–14,29." (PMID 29712934, 2018). "Direct mechanical damage to this area also caused insulin-resistant hyperglycemia and exhibited hormone level changes similar to those of CRS." (PMID 30618599, 2018). "The administration of PST in PST-deficient DIO mice or higher circulating level in DIO hyperglycemia and db/db mice inhibit insulin mediated PI3kinase activated signaling pathway." (PMID 29880906, 2018). "It is characterized by a combination of insulin resistance and insulin secretion defects, resulting in relative insulin deficiency and hyperglycemia." (PMID 29854726, 2018). "A decrease in insulin sensitivity occurs naturally, becoming evident in the second trimester, however, a noticeable loss of insulin sensitivity can lead to systemic resistance, hyperglycemia, and gestational diabetes mellitus (DM)." (PMID 30618791, 2018). "An insufficient release of insulin causes hyperglycemia, which results in oxidative damage by the generation of reactive oxygen species and the development of diabetic complications." (PMID 29890969, 2018). "In an abnormal, or insulin-resistant state, there is a loss of initial insulin secretion (first phase) in response to a glucose load, resulting in postprandial hyperglycemia." (PMID 30602666, 2018). "In GDM, there exists a relative deficiency of insulin to overcome this increased resistance, such that hyperglycaemia develops." (PMID 29882903, 2018). "By contrast, three months of hyperglycaemia in insulin-deficient Ins2Akita mice resulted in the downregulation of DNMT1 and DNMT3a expression." (PMID 30057682, 2018). "In the present model, hyperglycemia was associated with dyslipidemia, significant depletion of insulin, poor HOMA-β cell function and morphological damage and fibrotic pancreas." (PMID 29959408, 2018). "The observed increase in mortality associated with insulin-induced hypoglycemia provides a strong incentive to explore managing hyperglycemia with a reduced dependency on insulin." (PMID 29631990, 2018). "For example, intake of foods with high glycemic index is believed to predispose to postprandial hyperglycemia and higher insulin levels." (PMID 30314341, 2018). "Hypercortisolism is associated to hyperglycaemia and insulin resistance (IR), increasing glicogenolisis, and hepatic gluconeogenesis and playing a direct role on pancreatic insulin secretion." (PMID 30123187, 2018). "Hyperglycaemia associated with critical illness is commonly regarded as an extreme form of “stress hyperglycaemia”, typically attributed to insulin resistance caused by endogenous and exogenous catecholamines and glucocorticoids." (PMID 29713388, 2018).
Hyperglycemia (continued). "Despite differences on the underlying causing factors, all of them lead to hyperglycemia, which results from defects on insulin secretion, insulin resistance or a combination of both." (PMID 30429829, 2018). "To resolve these issues, we evaluated pancreatic insulin secretion and hepatic glycogen accumulation in the smoking rat model, and investigated the mechanism underlying the pathogenesis of hyperglycemia." (PMID 29437243, 2018). "After adjusting for other variables, age, HbA1c, type of surgical service, use of glucocorticoids, use of basal-bolus insulin therapy and year of surgery were significantly associated with hyperglycemia frequency." (PMID 29255628, 2018). "Unexpectedly, glimepiride exposure in mice was associated with fasting hyperglycemia, glucose intolerance, and decreased insulin." (PMID 30510962, 2018). "The choice of insulin regimen should be individualized and based upon cost, severity of hyperglycemia, risk of hypoglycemia, and likelihood of interventional procedures in the very near future." (PMID 29508275, 2018). "This assumption was hence confirmed in vivo, where treatment with PI3K inhibitors with systemic absorption is known to cause hyperglycemia and insulin insensitivity." (PMID 30542075, 2018). "This diabetic retinopathy includes protracted accumulation of leukocytes in retinal arteries when plasma insulin levels are high and pericyte apoptosis, linked to hyperglycemia induced accumulation of Reactive Oxygen Species (ROS), is evident." (PMID 29463026, 2018). "Loss of two Ins2 and Ins1 alleles in adult mouse β-cells causes loss of insulin production resulting in hyperglycemia." (PMID 30258344, 2018). "Disruption of rhythms in experimental animals causes hyperglycemia, hyperlipidemia, and other metabolic consequences, and in humans, T2D is associated with altered rhythms in insulin release." (PMID 30364286, 2018). "Mechanisms proposed to drive bone pathology in diabetic patients include deficiency in the secretion of insulin and insulin-like growth factor 1, impaired regulation of vitamin D and parathyroid hormone, and emergence of hyperglycemia." (PMID 29196931, 2018). "We observed that three months of hyperglycaemia, in insulin-deficient Ins2Akita mice, decrease DNMT1 and DNMT3a expression levels." (PMID 30057682, 2018). "Basal-bolus insulin therapy was associated with a 49% (95% CI: 1.44–1.59) increase in hyperglycemia frequency." (PMID 29255628, 2018). "Hyperglycemia associated with hyperinsulinemia observed in GDM mothers represents an insulin-resistant state as shown in several reports." (PMID 30539027, 2018). "While we did not reveal the dysregulation of DNMT expression using microarray data of short-term type 1 diabetes mouse models, three months of hyperglycaemia in insulin-deficient Ins2Akita mice resulted in the downregulation of DNMT1 and DNMT3a expression." (PMID 30057682, 2018). "In fact, we have reported that the HC diet promotes insulin release impairment, which causes hyperglycemia, by inducing bioenergetic deficiency in insulinoma cells." (PMID 29576853, 2018). "In the current study, protein restriction in the context of a high-fat diet (LP/HF) protected against hyperglycaemia and beta cell loss, and improved insulin sensitivity." (PMID 29550873, 2018). "Meanwhile, the hyperglycemia associated with T2DM is often treated with various forms of insulin as well as small molecule drugs that either increase insulin sensitivity (e.g., metformin) or assist with the excretion of excess sugars (e.g., canagliflozin)." (PMID 29963051, 2018). "These mice have an increase in G6pase and Pepck gene expression in the liver causing fasting hyperglycemia and, notably, insufficient insulin secretion to correct glycemia during intraperitoneal glucose tolerance tests." (PMID 29740399, 2018).
Hyperglycemia (continued). "While STZ is commonly used to induce a type 1 diabetic phenotype, the low-dose strategy adopted here causes a mild impairment of insulin secretion to bring about hyperglycemia." (PMID 30446513, 2018). "When hyperglycemia that resulted from insulin deficiency is partly relieved by exogenous insulin replacement, EDKA happens." (PMID 30369948, 2018). "The results of this study showed that oral insulin-loaded trimethyl chitosan nanoparticles, along with subcutaneous insulin, can reduce blood glucose and improve renal damage caused by hyperglycemia." (PMID 30524677, 2018). "This binding reduces the availability of insulin to its receptors in the liver and peripheral tissues causing hyperglycemia and additional secretion of insulin." (PMID 30462811, 2018). "Prolonged hyperglycaemia during critical periods of development underlie malformations in the foetal brain and insulin is also an important regulator of developmental and cognitive functions in the CNS." (PMID 28768549, 2017). "FEN did decrease fasting hyperglycaemia and markedly attenuated glucose intolerance in Leprdb mice, in association with increased serum insulin and increased pancreatic islet mass." (PMID 28256636, 2017). "The mediation effect of childhood insulin on the BMI-MetS and BMI-hyperglycemia associations was estimated at 19.2% (p < 0.001) and 18.3% (p < 0.001), respectively." (PMID 28230104, 2017). "Dietary Se deficiency globally down-regulate expression of selenoprotein encoding- and insulin signaling related- genes in pancreas, liver and muscle, resulting in dyslipidemia, hypoinsulinemia and hyperglycemia in chicken." (PMID 28763492, 2017). "Hyperglycemia associated with progressive resistance to insulin action and inappropriate insulin secretion is characterized as T2DM." (PMID 29082264, 2017). "The hyperglycemia observed following copanlisib infusion is likely caused by inhibition of insulin signaling and systemic insulin resistance, as previously reported in preclinical models of other PI3K/AKT pathway inhibitors." (PMID 27915408, 2017). "In both instances, it is thought that waking up early or sleeping late (during high melatonin and low insulin phase) predisposes to having meals, leads to high insulin levels and subsequent hyperglycemia, as a result of altered timing of food intake." (PMID 29194408, 2017). "On the other hand, in the HFD-obese model, hyperglycemia is associated with a rise in insulin level which appeared to be targeted/normalized by monoterpenes." (PMID 29267214, 2017). "We previously showed that ghrelin inhibits glucose-induced insulin secretion, and ghrelin ablation improves hyperglycemia of leptin-deficient mice." (PMID 28420089, 2017). "Streptozotocin-induced hyperglycemia, an insulin-deficiency DM model, increased liver metastasis of mouse colon cancer cells, while glycemic control with either insulin or gliclazide was protective." (PMID 28060743, 2017). "The HF-EFr diet significantly increased the phosphorylation of hepatic ERK1/2, which was associated with hyperglycemia and an increased insulin-to-C-peptide ratio." (PMID 28134848, 2017). "When high percentages of endogenous β-cells are destroyed, there will be little endogenous insulin production hence hyperglycaemia and weight loss." (PMID 28129400, 2017). "Defective insulin sensitivity in the liver results in increased glucose production, which is the major cause of hyperglycemia in diabetic patients." (PMID 28743992, 2017). "Hyperglycemia, a hallmark sign of DM, can be the result of impaired insulin secretion and/or insulin function." (PMID 28747209, 2017). "Ten days post STZ induction, the groups treated with STZ (45 & 55 mg/kg) developed frank hyperglycaemia with < 46.8% serum insulin, a severe deficiency typical of diabetes type 1." (PMID 28129400, 2017). "Insulin treatment improved hyperglycemia, secondary weight loss, and dyslipidemia caused by hyperglycemia in DIAR-nSTZ mice." (PMID 28903776, 2017).
Hyperglycemia (continued). "In patients with T2DM, hyperglycemia first becomes evident by an early loss in postprandial glucose control, which mainly results from a relative defect in insulin secretion duo to diet." (PMID 28629388, 2017). "T2D is a complex heterogeneous group of metabolic disorders including hyperglycemia and impaired insulin action and/or insulin secretion and causes dysfunctioning of multiple organs or tissues." (PMID 29082253, 2017). "In the three Get Goal studies, addition of lixisenatide to basal insulin led to an improvement in HbA1c and hyperglycemia after breakfast, as well as weight loss." (PMID 28115994, 2017). "Hyperglycemia has been identified as a key factor to induce to deficiency in insulin secretion and/or decreased reaction of the organs to insulin." (PMID 28333091, 2017). "Alloxan causes a massive reduction in insulin release because it destroys the β-cells of the islets of Langerhans, inducing hyperglycemia." (PMID 28208654, 2017). "Alloxan cause immense reduction in insulin release by the destruction of beta cells of the islets of langerhans and caused hyperglycemia." (PMID 28836990, 2017). "Insulin is the first-line therapy to control hyperglycemia but is associated with a risk of hypoglycemia." (PMID 28072822, 2017). "It caused a reduction in insulin release by a moderate destruction of β- cells of islets of langerhans, thereby, inducing hyperglycemia." (PMID 28629341, 2017). "In type 1 diabetes, the insulin-secreting pancreatic islets cease to produce the 51-amino-acid peptide that is need for the regulation of blood glucose, thereby resulting in a deficiency in insulin and putting the patient at risk of hyperglycemia." (PMID 28469179, 2017). "Type 1 diabetes (T1D) is an endocrine disease that results from autoimmune destruction of the pancreatic insulin-producing β-cells, leading to a loss of insulin secretion and symptomatic hyperglycemia." (PMID 28383493, 2017). "Insulin administration is the main treatment for T1D, although insulin is also provided in certain cases of T2D patients, when hyperglycemia cannot be controlled through diet, weight loss, exercise and oral medication." (PMID 28138367, 2017). "A mechanistic study in healthy volunteers showed that hyperglycemia associated with pasireotide subcutaneous (SC) is associated with decreases in insulin secretion but little change in insulin sensitivity." (PMID 27896545, 2017). "Any defect in the translocation of these glucose transporters (most importantly GLUT4) from the intracellular vesicles to the surface membrane is associated with insulin resistance, thereby leading to hyperglycaemia." (PMID 29058615, 2017). "Changes in plasma amino acid levels that correlate to increasing hyperglycemia have been described in insulin-deficient mice, and type 1 diabetes patients have been shown to have increased excretion of lysine in their urine." (PMID 28192442, 2017). "We used a mouse model mimicking human T2 diabetes, and characterized by hyperglycemia and abnormal insulin secretion caused by impaired β-cell function and insulin resistance." (PMID 28798347, 2017). "The mediation effect of childhood follow-up insulin was 19.2% (p < 0.001) on the childhood BMI-adult MetS association and 18.3% (p < 0.001) on the childhood BMI-adult hyperglycemia association." (PMID 28230104, 2017). "In this respect, chronic hyperglycemia leads to oxidative stress and gradual loss of pancreatic β-cell gene expression associated with impaired glucose-stimulated insulin secretion." (PMID 28788070, 2017). "Studies showed that the most important aspect of type 1 DM pathogenesis involved damage to β cells, resulting in decreases in their number and the secretion of insulin and causing symptoms related to hyperglycemia." (PMID 28758131, 2017). "Patients with DM exhibit hyperglycemia caused by an impairment in insulin secretion (type 1), insulin action (type 2), or both." (PMID 29036909, 2017).